COMMD1 (copper metabolism domain containing 1)
Diseases named in the same sentence as COMMD1 in open-access papers (continued):
Sharing a sentence is not in itself a finding about the gene and the disease.
cancer (continued). "Recently, it has been reported that a decreased expression of COMMD1 is frequently observed in a variety of cancers and that this correlates with tumor invasion as well as with the overall patient survival." (PMID 23401744, 2013). "Consistent with the notion that COMMD1 functions in multiple cellular pathways involved in the survival of cancer cells, it has been demonstrated that the decreased COMMD1 expression in human cancer correlates with a more invasive tumor phenotype." (PMID 23401744, 2013). "The cellular accumulation of COMMD1 was also found in situ immunofluorescence in human cancer cells." (PMID 23401744, 2013). "In addition, downregulation of the copper-containing metabolism MURR1 structural domain 1 (COMMD1) in cancer cells enhances the inflammatory response and creates favorable conditions for macrophage recruitment." (PMID 37822927, 2023). "For instance, COMMD1 inhibits the development of cancer in a number of malignancies." (PMID 36776284, 2023). "For example, overexpression of COMMD1 in colorectal cancer, glioblastoma, and melanoma could suppress cancer cells invasion and metastasis by directly inhibiting HIF-mediated gene expression." (PMID 34493238, 2021). "Since higher mRNA levels of COMMD proteins were found in patients with a more advanced cancer grade and the cohort of individuals with grade 4 disease was small, we further explored the correlation between the mRNA levels of COMMD1–10 and the survival of HCC patients with grade 3 disease." (PMID 34493238, 2021). "Furthermore, COMMD1 has been shown to be suppressed in human cancer and its decreased expression to correlate with a more invasive tumor phenotype." (PMID 29050225, 2017). "This decreased COMMD1 expression is correlated with cancer behavior and reduced survival rate." (PMID 27788210, 2016). "One of the proposed mechanisms of COMMD1 in mediating the behavior of cancer involves its inhibitory action on the activity of the transcription factors hypoxia inducible factor 1 (HIF-1) and nuclear factor kappa-light-chain-enhancer of activated B cells (NF-κB)." (PMID 27788210, 2016). "Interestingly, however, we detected a marked nuclear expression of COMMD1 in a subset of cancer tissue samples, in addition to cytoplasmic staining of COMMD1." (PMID 27788210, 2016). "The stabilization and nuclear accumulation of COMMD1 mediated by CIGB-552 could be an attractive mechanism for the regulation of the constitutive activity of the transcription factor NF-κB in cancer cells." (PMID 23401744, 2013). "First, the cellular expression of COMMD1 in whole-cell lysates of human cancer cells of different histological origin was determined using Western blot analysis, and the proteasome inhibitor MG132 which induces the accumulation of COMMD1 was used as a positive control." (PMID 23401744, 2013). "This suggests that decreased COMMD1 expression might represent a novel mechanism that confers cancer cells with invasion potential and proliferating capacity." (PMID 23401744, 2013). "Takamitsu Miyayama and Amila Suraweera found that COMMD1 knockdown decreased ATP7B expression and enhanced the effectiveness of cisplatin and radiotherapy on cancer cells." (PMID 40109870, 2025). "COMMD1, COMMD5, and COMMD10 are known to act as tumor suppressors, and their expression levels are reduced in several cancers including cancers, seminoma, melanoma, as well as kidney, pancreatic, colorectal, and ovarian cancers." (PMID 34943955, 2021). "Taken together, COMMD1 functions in DSB repair, is a prognostic maker in NSCLC and is potentially a novel anti-cancer therapeutic target for NSCLC." (PMID 33669398, 2021). "Next, we analyzed the relationship between the mRNA expression of COMMD1–10 and clinicopathological parameters of HCC patients (individual cancer stage and tumor grade) through UALCAN, including patients’ individual cancer stage and tumor grade." (PMID 34493238, 2021).
cancer (continued). "Interestingly, the peptides derived from LALF32–51 region were found to bind COMM domain (amino acids 119–190) and, more important, our results provide the first indication that CIGB-552 could regulate the levels of COMMD1 to induce the cell death in cancer cells." (PMID 23401744, 2013). "Similar to COMMD1, COMMD10 plays a role in cancer by targeting the NF-κB pathway." (PMID 34493238, 2021). "CIGB-552 was undoubtedly found to accumulate COMMD1 in cancer cells and this accumulation was not accompanied by changes in the mRNA expression." (PMID 23401744, 2013). "However, the impact of COMMD1 on cancer progression has not been consistently studied, highlighting the need for further research on this protein." (PMID 40109870, 2025). "Since the COMMD family members COMMD1 and COMMD4 had been reported to be involved in DNA damage repair to maintain the genome stability of the cancer cells, we wondered whether COMMD10 plays a role in DNA damage in GC cells." (PMID 38871970, 2024). "In addition, the interaction between CIGB-552 and COMMD1 was also confirmed in whole-cell lysates of human cancer cells of different histological origins (data not shown)." (PMID 23401744, 2013).
tumor (22 papers, 2013 to 2025). "We then demonstrate that COMMD1 can influence the biological activity of tumor cells using a series of biological experiments such as CCK8, EdU, clone formation, migration, and invasion." (PMID 40109870, 2025). "In this study, we performed silico analyses and basic biological experiments, and suggested that alterations in the expression of COMMD1 play a key role in tumorigenesis, progression, and prognosis, and COMMD1 can be used as a predictor of tumor prognosis." (PMID 40109870, 2025). "To explore molecular biological pathways for downregulation of miR-200c and COMMD1, we performed RNAseq with these four groups of tumor tissues." (PMID 38476765, 2024). "The canonical family member COMMD1 is a tumour suppressor with cytoplasmic roles controlling vesicular trafficking, and nuclear roles restraining HIF-1α and NFkB activity." (PMID 37072858, 2023). "COMMD1 acts as a tumor suppressor by inhibiting NF-kB and Hypoxia-inducible factor (HIF) mediated gene expression." (PMID 34943955, 2021). "COMMD1 has been demonstrated to inhibit HIF-1 transcription activity by competing with HIF-1β for binding to HIF-1α in human tumor cells." (PMID 33716719, 2021). "To this end, we assessed the cytoplasmic and nuclear COMMD1 expression in chemo-naive tumor samples of 126 retrospectively selected advanced stage HGSOC patients (tissue microarray #1, TMA1)." (PMID 27788210, 2016). "Of those tumors with positive COMMD1 expression, cytoplasmic COMMD1 staining was readily detected (>75% of tumor cells stained positive) in all patients and only differed in intensity." (PMID 27788210, 2016). "COMMD1 downregulation promoted tumorigenicity and tumor growth and increased inflammation and stemness." (PMID 28116318, 2016). "The prognostic significance of COMMD1 expression and correlation with mRNA data were assessed by computerized image analysis of COMMD1 positivity in the tumour tissue." (PMID 24625556, 2014). "Subgroup dot plots showed the difference in COMMD1 expression between tumor and normal tissues." (PMID 40109870, 2025). "As a result, COMMD1 could potentially influence tumor tissue invasiveness through the regulation of copper ion levels and changes in mitochondrial metabolism." (PMID 40109870, 2025). "We report here that miR-200c in fibroblasts as a novel positive regulator of NFκB-HIF signaling via COMMD1 depletion, recapitulates the cardinal inflammatory-glycolytic features of CAFs and promotes tumor growth, metastasis and resistance to immuno-chemotherapy." (PMID 38476765, 2024). "HIF-1, a transcription factor, is similarly regulated by COMMD1 in tumor cells." (PMID 36776284, 2023). "Its anti-tumor activity is, at least in part, mediated by the stabilization of the COMMD1 protein." (PMID 33396282, 2020). "A cell-type specific role of COMMD1 in tumor behavior is corroborated by prior studies." (PMID 27788210, 2016). "In 94% of these tumor samples, COMMD1 expression was detected." (PMID 27788210, 2016). "Interestingly, COMMD1-KD in the context of anti-miR-200c rescued tumor growth." (PMID 38476765, 2024). "Similarly, the mRNA expression levels of COMMD1–10 were significantly related to tumor grade." (PMID 34493238, 2021). "However, the minimal effect that the peptide had on COMMD1 KO gene expression may support the relevant role of COMMD1 in the anti-tumor activity triggered by CIGB-552." (PMID 33396282, 2020). "Therefore, the aim of the present work was to evaluate the relationship between the cell penetrating capacity of CIGB-552, the internalization mechanisms involved, and COMMD1 expression on three different tumor-derived cell lines with dissimilar sensitivity to the peptide: MCF-7, HT-29 and H460." (PMID 29601540, 2018). "Although the majority of molecular mechanism research have focused on COMMD1, nearly all COMMD protein family members regulate tumor progression." (PMID 36776284, 2023).
tumor (continued). "Two proteins that interact with HMGB2, COMMD1 and MIEN1, are identified in SKOV-3 and tumor tissue libraries, which cross-validate these results." (PMID 32867128, 2020). "Further, researchers found that COMM domain-containing 1 (COMMD1) disrupted the dimerization of HIF-1α and HIF-1β, which then inhibited NF-κB mediated gene expression and tumor cell invasion." (PMID 32127518, 2020). "COMMD1 was shown to inhibit HIF-mediated gene expression, resulting in reduction of tumor metastases." (PMID 29050225, 2017). "COMMD1 can disrupt HIF-1α/β dimerization and inhibit human tumor cell invasion." (PMID 35399735, 2022). "TMA analysis of NSCLC patient samples corroborated our mRNA and immunoblotting analyses, where COMMD1 levels were high irrespective of age, tumor grade, surgical stage or the TNM score." (PMID 33669398, 2021). "Using semi-quantitative analysis of COMMD1 immunohistochemical stainings, we indeed found consistently lower levels of nuclear COMMD1 in ‘nuclear COMMD1-negative’ tumor samples when compared to ‘nuclear COMMD1-positive’ tumor samples." (PMID 27788210, 2016). "The meta-analysis of COMMD1 transcripts demonstrated that NSCLC patients had significantly higher levels of COMMD1 than control normal tissue, irrespective of the NSCLC subtype or the tumor grade." (PMID 33669398, 2021).
liver (1 paper, 2020). "Another protein (COMMD1, formerly MURR1) is also necessary for biliary Cu excretion, as first demonstrated in Bedlington terriers suffering from liver Cu toxicosis." (PMID 32668621, 2020).
COMMD1 also shares sentences with these, for which no sentence is quoted: Age-related nuclear cataract (1 paper); Ascites (1); autism (1); cerebral infarction (1); fibrosis (1); follicular lymphoma (1); glioblastoma (1); hemochromatosis (1); Hepatic failure (1); HIV-1 infection (1); myocardial infarction (1); portal hypertension (1); psoriasis (1); seminoma (1); Sepsis (1); serous ovarian cancer (1); Zinc deficiency (1).